CORO2B (coronin 2B)
Description:
May play a role in the reorganization of neuronal actin structure.
Synonyms: KIAA0925; ClipinC
Tractability: Antibody: the Human Protein Atlas places it where antibodies can reach. PROTAC: ubiquitination databases record sites on it; its protein half-life has been measured.
Gene: Protein-coding gene on chromosome 15 (68,578,971 to 68,727,806, forward strand). Ensembl gene ENSG00000103647.
Subcellular location: Cytoplasm, cytoskeleton
Subcellular location (Human Protein Atlas): Focal adhesion sites; Plasma membrane
Gene Ontology:
Molecular function: protein binding; talin binding; vinculin binding; actin binding; actin filament binding
Biological process: negative regulation of cell-substrate adhesion; negative regulation of establishment of protein localization; positive regulation of establishment of protein localization; regulation of actin cytoskeleton organization; regulation of cellular response to stress; actin cytoskeleton organization; actin filament organization; focal adhesion assembly
Cellular component: focal adhesion; actin cytoskeleton; actin filament; membrane; plasma membrane; cytoskeleton
Genetic constraint (gnomAD): Loss-of-function variants: 26 observed, 56.97 expected, observed/expected ratio (o/e) 0.46, 90% interval 0.33 to 0.63. The upper end of that interval is the gene's LOEUF score, 0.63, which puts it in group 2 of 6, group 1 being the genes least tolerant of losing a copy. Missense variants: 456 observed, 667.03 expected, observed/expected ratio (o/e) 0.68, 90% interval 0.63 to 0.74. Synonymous variants: 242 observed, 261.58 expected, observed/expected ratio (o/e) 0.93, 90% interval 0.83 to 1.03.
Homologues: Orthologues: chimpanzee CORO2B (100% identical), macaque CORO2B (99% identical), pig CORO2B (99% identical), rat Coro2b (98% identical), mouse Coro2b (98% identical), guinea pig CORO2B (98% identical), dog CORO2B (94% identical), zebrafish coro2ba (86% identical), tropical clawed frog coro2b (85% identical), rabbit CORO2B (83% identical), zebrafish coro2bb (67% identical), Drosophila melanogaster coro (44% identical), and 1 more. Paralogues in human: CORO2A (66% identical), CORO1C (44% identical), CORO6 (44% identical), CORO1B (43% identical), CORO1A (42% identical), CORO7 (31% identical).
Diseases named in the same sentence as CORO2B in open-access papers:
CORO2B is named in the same sentence as 11 diseases in open-access papers, as found by Europe PMC text mining. Sharing a sentence is not in itself a finding about the gene and the disease. The quoted sentences say what the papers report.
glomerular disease (2 papers, 2017 to 2019). "To analyze the role of Coro2b in acquired human glomerular diseases, we studied the expression pattern of Coro2b using immunoperoxidase staining in renal biopsies collected from patients with DN, IgA nephropathy (IgAN) and membranous nephropathy (MN)." (PMID 31221975, 2019). "In contrast to Coro2b, staining for synaptopodin, another podocyte specific protein, showed only modest reduction in all three glomerulopathies." (PMID 31221975, 2019). "Taken together, our study suggests a role for Coro2b in the pathogenesis of glomerulopathies." (PMID 31221975, 2019). "Our study suggests a potential role for Coro2b in the pathogenesis of glomerular diseases." (PMID 31221975, 2019). "In addition, CFL1 phosphorylation (indicating CFL1 inactivation) was observed in human glomerular disease samples and resembled cellular phenotypes of Coro2b knockout cell." (PMID 29162887, 2017).
Nephropathy (2 papers, 2017 to 2019). A nonspecific term referring to disease or damage of the kidneys. "To test for a possible role of Coro2b in glomerular stress response we exposed control and Coro2b deficient animals to the established Doxorubicin-nephropathy model." (PMID 29162887, 2017). "Analysis of a novel Coro2b knockout mouse revealed that CORO2B modulates stress response of podocytes in an experimental nephropathy model." (PMID 29162887, 2017). "Applying the Doxorubicin nephropathy model we tested for a potential role of Coro2b in podocyte stress conditions." (PMID 29162887, 2017). "Coro2b-deficiency did not affect the development of nephropathy in the STZ-induced diabetes mouse model, which argues against the idea that Coro2b has a pathogenic role in the progression of DN." (PMID 31221975, 2019). "Taken together, absence of Coro2b in podocytes did not affect the outcome of nephropathy in a STZ-induced model of diabetes." (PMID 31221975, 2019). "Moreover, inactivation of Coro2b specifically in podocytes does not affect the outcome of nephropathy in a streptozotocin-induced diabetes model." (PMID 31221975, 2019).
cerebral malaria (1 paper, 2020). A sequestration of Plasmodium falciparum in the brain, which can cause coma and/or seizures. "In addition, CORO2B plays a key role in brain endothelial cells of cerebral malaria." (PMID 32309439, 2020).
diabetes (1 paper, 2019). "We detected a trend for down-regulation of Coro2b expression in glomeruli after induction of diabetes in wild type mice but this was not statistically significant." (PMID 31221975, 2019).
cancer (1 paper, 2021). A tumor composed of atypical neoplastic, often pleomorphic cells that invade other tissues. "For other coronin families that have not been analyzed in this study (especially, CORO1C, CORO2B, and CORO7 whose expressions are dysregulated in cancer tissues), it is essential to elucidate the molecular pathogenesis of OSCC." (PMID 34884487, 2021).
CORO2B also shares sentences with these, for which no sentence is quoted: ciliopathies (2 papers); diabetic nephropathy (1); glomerulopathies (1); IgA nephropathy (1); Intellectual disability (1); membranous nephropathy (1).